FPR1 (formyl peptide receptor 1)
Diseases named in the same sentence as FPR1 in open-access papers (continued):
Sharing a sentence is not in itself a finding about the gene and the disease.
periodontitis (12 papers, 2015 to 2025). An acute or chronic inflammatory process that affects the tissues that surround and support the teeth. "The key associated pathways include proteins involved in periodontitis, chronic bronchitis, prostate cancer, dental caries, ulcerative colitis, presbycusis, neutrophil degranulation via FPR1 signaling and amyloid beta clearance in Alzheimer’s disease." (PMID 41552085, 2025). "Genetic variations in the Fmlp receptor (FPR1) gene are strongly linked to increased susceptibility to periodontitis and peri-implantitis." (PMID 39650553, 2024). "Although the type of periodontitis was different, the genetic variations in FPR1 from periodontitis patients had a common feature; the mutations caused the receptor to malfunction." (PMID 33082511, 2020). "FPR1, a bacterial peptide sensor, drives neutrophil chemotaxis toward inflamed sites, amplifying neutrophil recruitment in periodontitis." (PMID 41009952, 2025). "Reports on FPRs in the oral cavity have focused on very narrow aspects: reports on FPR1 have focused on periodontitis, and reports on FPR2 have focused on submandibular gland and saliva production." (PMID 33082511, 2020). "From these findings, researchers uncovered genetic variations in the FPR1 gene in periodontitis patients." (PMID 33082511, 2020). "Since the 1970s, it has been well known that neutrophils from periodontitis patients have defective FPR1 signaling." (PMID 33082511, 2020). "Meanwhile, four genes, including FPR1, AQP9, BCL2A1, and VNN2 showed significantly higher expression in periodontitis patients and were strongly correlated with neutrophil infiltration, emerging as central to diagnosis and understanding of periodontitis." (PMID 41009952, 2025).
melanoma (10 papers, 2010 to 2023). A malignant, usually aggressive tumor composed of atypical, neoplastic melanocytes. "FPR1 is overexpressed in human primary melanoma and associates with aggressive phenotype." (PMID 29216889, 2017). "Neutrophil co-culture enhanced the melanoma cell invasion, which was inhibited if melanoma cells were pre-treated with FPR1 and FPR2 antagonists." (PMID 36766767, 2023). "The antagonisms of FPR1 or FPR2 also inhibited the augmented invasiveness of melanoma cells co-cultured with neutrophils or incubated with NCM." (PMID 36766767, 2023). "More recently, Carriero’s group showed that the association of uPAR with the overexpressed FPR1 leads to the melanoma and ovarian cancer cell invasion, that is inhibited by the potent RI-3 peptide, disrupting the uPAR84–95/FPR1 interaction." (PMID 35493073, 2022). "It has been assessed that FPR1 is involved in the progression of solid tumors including glioblastoma, neuroblastoma, sarcoma, melanoma and ovarian cancer." (PMID 35158766, 2022). "A polyclonal antibody recognizing the uPAR84–95 sequence abolishes uPAR binding to FPR1 and prevents uPA-dependent cell adhesion and migration, the chemotaxis of melanoma cells and the invasion of matrices and endothelial monolayers." (PMID 35158766, 2022). "RI-3 adopts a turn structure very similar to that adopted by previous characterized uPAR-FPR1 antagonists, is stable in human serum, prevents the uPAR/FPR1 interaction and potently inhibits migration and invasion of human sarcoma and melanoma cells." (PMID 31434916, 2019). "3D reconstruction of z-stack analysis confirmed that the internalization of FPR1 does occur in both melanoma cell lines (right)." (PMID 29216889, 2017). "We found that the co-expression of uPAR and FPR1 confers to melanoma cells the capability to move towards chemotactic gradients, to cross ECM and endothelial monolayers." (PMID 29216889, 2017). "We found that the co-expression of uPAR and FPR1 confers to A375 and M14 melanoma cells a clear-cut capability to move towards chemotactic gradients, to cross extracellular matrix and endothelial monolayers." (PMID 29216889, 2017). "Hence, we addressed this issue, showing AnxA1 secreted by neutrophils contributes to the development of melanoma lung metastasis by promoting cancer invasiveness through FPR1/FPR2 pathways." (PMID 36766767, 2023). "Both uPAR and FPR1 are involved in melanoma tumor progression, suggesting that they may be targeted for therapeutic purposes." (PMID 29216889, 2017). "Collectively, our findings identify uPAR and FPR1 as relevant effectors of melanoma cell invasiveness and suggest that inhibitors of the uPAR84–95/FPR1 cross-talk may be useful for the treatment of metastatic melanoma." (PMID 29216889, 2017). "Collectively, our findings identify uPAR and FPR1 as novel prognostic markers and therapeutic targets in melanoma and indicate that inhibitors of the uPAR84–95/FPR1 cross-talk may be useful for the treatment of metastatic melanoma." (PMID 29216889, 2017). "The main focus of this study was to elucidate the role of the uPAR-FPR1 cross-talk in sustaining melanoma cell ability to invade extracellular matrix and cross endothelial barriers, focusing on the function of the uPAR84–95 sequence which we and others have previously reported to signal trough FPR1." (PMID 29216889, 2017). "Thus, the uPAR84–95/FPR1 complex may be considered an attractive therapeutic target for melanoma cells." (PMID 29216889, 2017). "Also, the possibility that inhibition of the uPAR mediated FPR1-dependent signaling may prevent matrix invasion and transendothelial migration of melanoma cells was investigated." (PMID 29216889, 2017). "For this, murine melanoma B16F10 cells were applied, in which AnxA1 and its receptors (FPR1 and FPR2) were first characterized." (PMID 36766767, 2023).
melanoma (continued). "Finally, melanoma cell ability to move toward chemotactic gradients, invade matrigel or fibroblast-embedded collagen matrices and cross endothelial monolayers are prevented by anti-uPAR84–95 antibodies or by the RI-3 peptide which we have previously shown to inhibit the uPAR84–95/FPR1 interaction." (PMID 29216889, 2017). "Together with the many so far reported pro-tumoral activities of uPAR, our observations make the uPAR/FPR1 system an attractive target for the treatment of melanoma that has not yet been extensively explored in the clinic." (PMID 29216889, 2017). "In fact, both uPAR expressing and uPAR lacking melanoma cells respond to FPR1 agonist SRSRY, their motility being abrogated by FPR1 desensitization." (PMID 29216889, 2017).
neuroblastoma (9 papers, 2016 to 2021). Neuroblastoma (NB) is the most common solid, extracranial childhood tumor. "Neuroblastoma primary tumors and cell lines have been found to express FPR1; increased expression of which is correlated with high-risk disease and low survival rates." (PMID 31170199, 2019). "In this study, we investigated the functional role of FPR1 in neuroblastoma development, and showed that high FPR1 expression is associated with high-risk disease and is important for neuroblastoma tumorigenesis." (PMID 27432059, 2016). "Knockdown of FPR1 with shRNA delayed neuroblastoma development, while ectopic overexpression of FPR1 elicited augmented tumorigenesis in nude mice." (PMID 31170199, 2019). "To investigate the function of FPR1 in neuroblastoma, we stimulated neuroblastoma cells with the FPR1 agonist fMLP." (PMID 27432059, 2016). "The tumorigenic capacity of FPR1 was assessed by xenografting of neuroblastoma cells expressing inducible FPR1 shRNA, FPR1 cDNA or control shRNA in nude mice." (PMID 27432059, 2016). "Immunohistochemistry and immunofluorescence showed a high expression of FPR1 in neuroblastoma tissue samples and cell lines, respectively." (PMID 27432059, 2016). "By immunohistochemistry, we analyzed neuroblastoma primary tumors from different biological subsets and clinical stages, and FPR1 expression was detected in all the samples investigated (n = 27), independent of any biological characteristics or clinical stage." (PMID 27432059, 2016). "shRNA knock-down of FPR1 in neuroblastoma cells conferred a delayed xenograft tumor development in nude mice, whereas an ectopic overexpression of FPR1 promoted augmented tumorigenesis in nude mice." (PMID 27432059, 2016). "Calcium mobilization assays and western blots with phospho-specific antibodies were used to assess the functional activity of FPR1 in neuroblastoma." (PMID 27432059, 2016). "Using publicly available expression cohorts, we analyzed the expression levels of FPR1 and the correlation to overall survival in neuroblastoma patients." (PMID 27432059, 2016). "The level of FPR1 expression was shown to be lower in benign neurofibroma and normal neural crest than in the neuroblastoma, indicating a role of FPR1 in the process of tumorigenesis." (PMID 27432059, 2016). "Expression of FPR1 in neuroblastoma cell lines and primary tumors was studied using RT-PCR, western blotting, immunofluorescence and immunohistochemistry." (PMID 27432059, 2016). "FPR1 found in neural glial cells, astrocytes and neuroblastoma." (PMID 32697195, 2020). "Increased FPR1 expression in neuroblastoma primary tumours is correlated with high-invasiveness and low patient survival rates, which may be influenced by the FPR-induced differentiation reported here." (PMID 31170199, 2019). "Our data demonstrate that FPR1 is involved in neuroblastoma development and could represent a therapy option for the treatment of neuroblastoma." (PMID 27432059, 2016). "Furthermore, all neuroblastoma cell lines analyzed exhibited a significant expression of FPR1, as shown by RT-PCR and western blotting." (PMID 27432059, 2016). "Stimulation of FPR1 in neuroblastoma cells using fMLP, a selective FPR1 agonist, induced intracellular calcium mobilization and activation of MAPK/Erk, PI3K/Akt and P38-MAPK signal transduction pathways that were inhibited by using Cyclosporin H, a selective receptor antagonist for FPR1." (PMID 27432059, 2016). "Also, the expression level of FPR1 was analysed in a benign neurofibroma and neural crest revealing a significant lower expression levels compared to neuroblastoma." (PMID 27432059, 2016). "FPR1 is expressed in neuroblastoma primary tumors and cell lines." (PMID 27432059, 2016). "This analysis revealed that 1.918 of the 18.469 differentially expressed neuroblastoma transcripts were neutrophil-related, which included highly specific neutrophil markers such as FCGR3B, FPR1, S100A8/9, and SIGLEC9, among others." (PMID 34503071, 2021).
neuroblastoma (continued). "Herein, we demonstrate that in neuroblastoma SH-SY5Y cell line, FPR1 stimulation by its agonist results in NOX2-dependent ROS generation and, in turn, in TrkA transactivation." (PMID 31871542, 2019). "Herein, we show that the SH-SY5Y neuroblastoma cell line expresses NOX2 components, FPR1, and TrkA, and that FPR1 stimulation by formylated peptides induces NADPH-dependent ROS generation, as well as the phosphorylation of Y490, Y751, and Y785 residues of TrkA." (PMID 31871542, 2019).
ovarian carcinoma (9 papers, 2012 to 2025). A malignant neoplasm originating from the surface ovarian epithelium. "In order to assess whether the uPAR/FPR1 crosstalk dictates the capability of ovarian cancer cells to adhere onto Vn and mesothelium, a series of adhesion experiments was performed in the presence or the absence of 10 nM RI-3." (PMID 31703596, 2019). "While the role of uPAR in favoring intra-abdominal dissemination of ovarian cancer cells is largely documented, no data regarding expression and possible role of FPR1 on the surface of ovarian cancer cells are currently available." (PMID 31703596, 2019). "While the uPAR role in promoting intra-abdominal dissemination of ovarian cancer cells is largely documented, to the best of our knowledge, the expression of FPR1 in EOC tissues has never been reported." (PMID 31703596, 2019). "Confirmatory experiments were performed using A2780 human ovarian carcinoma cells which neither express uPAR nor FPR1 on cell surface, as shown by Fax analysis." (PMID 31703596, 2019).
pulmonary fibrosis (9 papers, 2020 to 2025). Chronic progressive interstitial lung disorder characterized by the replacement of the lung tissue by connective tissue, leading to progressive dyspnea, respiratory failure, or right heart failure. "FPR1‐deficient mice are protected from bleomycin‐induced pulmonary fibrosis, with impaired neutrophil recruitment to the lungs." (PMID 41088837, 2025). "The formyl peptide receptor 1 (FPR1) expressed on neutrophils is instrumental in their recruitment into pulmonary fibrotic tissues, and a deficiency in FPR1 has been shown to confer protection against the development of pulmonary fibrosis." (PMID 41394824, 2025). "FPR-1–deficient (fpr1–/–) mice are protected from bleomycin-induced pulmonary fibrosis but can develop renal and hepatic fibrosis as normal with the model utilised." (PMID 34367163, 2021). "FPR-1–deficient (fpr1–/–) mice were protected from bleomycin-induced pulmonary fibrosis but developed renal and hepatic fibrosis normally." (PMID 32102985, 2020). "Importantly, FPR1 appears to be uniquely implicated in lung fibrosis." (PMID 41088837, 2025). "In contrast, neutrophil recruitment to the liver and kidney remains unaffected, and fibrosis in these organs develops normally, underscoring the tissue‐specific role of FPR1 in driving pulmonary fibrosis." (PMID 41088837, 2025). "Here, we provide strong experimental evidence that FPR-1 is essential for participation of neutrophils in lung fibrosis and suggest that the receptor and/or its ligands are rational therapeutic targets." (PMID 32102985, 2020). "Mechanistically, we show that FPR-1 is required for effective homing of neutrophils to damaged lung tissue and that depletion of neutrophils protects mice from bleomycin-induced pulmonary fibrosis." (PMID 32102985, 2020). "In this study, we describe a tissue-specific role for FPR-1 in the development of pulmonary fibrosis, with FPR-1 being entirely dispensable in the development of hepatic and renal fibrosis." (PMID 32102985, 2020). "Moreover, a recent report has implicated the regulatory role of FPR1 in protecting hosts from bleomycin-induced pulmonary fibrosis where neutrophil-specific FPR1 plays a role in scar formation." (PMID 38853986, 2024). "In the pulmonary fibrosis model, FPR1–/– mice are exempt from bleomycin-induced pulmonary fibrosis." (PMID 35186710, 2021). "Moreover, we show that fpr1–/– mice and neutrophil-depleted C57BL/6 WT mice are protected from bleomycin-induced pulmonary fibrosis, highlighting the potential therapeutic benefit of targeting FPR-1 or neutrophils in the fibrotic lung." (PMID 32102985, 2020). "FPR-1 is the primary receptor driving neutrophil recruitment to the injured lung, and absence of FPR-1 or depletion of neutrophils protects from pulmonary fibrosis." (PMID 32102985, 2020).
emphysema (8 papers, 2011 to 2024). "While little is known about the role of FPR2 in COPD, it has been shown that FPR1 downregulation provides protection against emphysema in a mouse model." (PMID 33078507, 2021). "However, one study showed that the genetic ablation of FPR1 in mice provided protection against cigarette smoke‐induced emphysema and airway inflammation." (PMID 33078507, 2021). "The relationship between smoking and emphysema is based on the expression levels of fMLP and FPR1." (PMID 33082511, 2020). "In addition, Fpr1−/− mice have decreased inflammation and emphysema compared to control mice after cigarette smoke exposure." (PMID 28793908, 2017). "In this line, higher binding of the fLMF peptide has been observed in leukocytes from patients suffering from Crohn’s disease or emphysema indicating that FPR1 expression on leukocytes may serve as a marker for systemic inflammation." (PMID 23185575, 2012). "FPR1 has been demonstrated to be an important receptor in COPD, because genetic ablation of this receptor confers protection from the development of cigarette smoke-induced emphysema in the mouse model." (PMID 29544524, 2018).
Crohn disease (7 papers, 2012 to 2025). A gastrointestinal disorder characterized by chronic inflammation involving all layers of the intestinal wall, noncaseating granulomas affecting the intestinal wall and regional lymph nodes, and transmural fibrosis. "Crohn’s disease patients show a high expression level of FPR1 in neutrophils; moreover, ulcerative colitis (UC) patients display an exacerbate activation of FPR1 in their intestines." (PMID 41425092, 2025). "Herein, we demonstrate that higher levels of colonic formyl peptide receptor 1 and annexin A1 correlate with histological recovery in Crohn’s disease patients under remission." (PMID 34603288, 2021).
myocardial infarction (7 papers, 2021 to 2025). Gross necrosis of the myocardium, as a result of interruption of the blood supply to the area, as in coronary thrombosis. "The first-generation of FPR2 small-molecule agonists also show heart-protective properties in acute myocardial infarct and compound 43, a dual FPR1/FPR2 agonist, provides a high degree of protection in a model of heart failure." (PMID 33804219, 2021). "However, FPR1 activation has been shown to improve left ventricular remodeling after myocardial infarction in mice and rats, potentially by promoting early neutrophil migration and infiltration, thus accelerating wound healing." (PMID 40630963, 2025).
asthma (6 papers, 2021 to 2025). "Although FPR1 was reported to react to cigarette smoke and be involved in the anti-inflammatory activities of glucocorticoids, little is known about its effect on asthma." (PMID 33602227, 2021). "SMR results suggested that therapies targeting FPR1, IL1RAP, IL7R, and IL18RAP inflammatory variables may be able to prevent an increase in AD in moderate to severe asthma." (PMID 40951943, 2025). "Among these targets, FPR1 (Formyl Peptide Receptor 1), IL1RAP (Interleukin 1 Receptor Accessory Protein), IL7R (Interleukin 7 Receptor), and IL18RAP (Interleukin 18 Receptor Accessory Protein) warrant additional exploration as potential therapeutic targets for AD and moderate to severe asthma." (PMID 40951943, 2025). "Furthermore, we examined Th1-high vs. Th1-low asthma patients but did not detect a significant difference in receptor expression between these groups, neither in BLT1 nor FPR1 expression." (PMID 36304163, 2022).
lung carcinoma (6 papers, 2020 to 2025). "FPR1 is highly expressed in the blood of non-small cell lung cancer patients and can be used as a single biomarker for the detection of lung cancer." (PMID 37747648, 2023). "Morris and other studies have shown that elevated levels of FPR1 mRNA can predict the diagnosis of lung cancer, with a sensitivity of 55% and a specificity of 87% in the validation sample set." (PMID 35186710, 2021). "Additionally, under hypoxic conditions, SIRT3 influences lung cancer progression through the ROS/formyl peptide receptor-1 (FPR1)/HIF-1α axis." (PMID 40710178, 2025). "We explored whether SIRT3 affects the development of lung cancer by regulating the reactive oxygen species (ROS)-FPR1/HIF-1α axis under hypoxic conditions." (PMID 37747648, 2023). "However, the roles of FPR1 in relation to oxidative stress and inflammation in hypoxia-induced lung cancer cells are unclear." (PMID 37747648, 2023).